PSPHP1 (phosphoserine phosphatase pseudogene 1)
Synonyms: CO9; PSPHL
Gene: Transcribed unprocessed pseudogene on chromosome 7 (55,764,797 to 55,773,288, forward strand). Ensembl gene ENSG00000226278.
Diseases named in the same sentence as PSPHP1 in open-access papers:
PSPHP1 is named in the same sentence as 20 diseases in open-access papers, as found by Europe PMC text mining. Sharing a sentence is not in itself a finding about the gene and the disease. The quoted sentences say what the papers report.
lymphoma (1 paper, 2025). A malignant (clonal) proliferation of B- lymphocytes or T- lymphocytes which involves the lymph nodes, bone marrow and/or extranodal sites. "Furthermore, by conducting summary‐data‐based Mendelian randomisation (SMR) analysis, we have identified novel genes that regulate immune cell function, including PSPHP1 and AGAP6, which have not been previously investigated in the context of lymphoma." (PMID 40360443, 2025).
PSPHP1 also shares sentences with these, for which no sentence is quoted: breast carcinoma (10 papers); tumor (8); cancer (5); breast tumors (4); prostate carcinoma (4); endometrial cancer (2); glioblastoma (2); glioma (2); low grade glioma (2); ovarian carcinoma (2); pilocytic astrocytoma (2); Cognitive impairment (1); COVID-19 (1); Fanconi anemia (1); gastric cancer (1); invasive breast carcinoma (1); prostate tumors (1); psoriasis (1); serous ovarian cancers (1).